CRISP3 (cysteine rich secretory protein 3)
Synonyms: CRISP-3; SGP28; CRS3; dJ442L6.3; Aeg2
Tractability: Antibody: its Gene Ontology location is reachable by antibodies, with high confidence; UniProt places it where antibodies can reach, with medium confidence; UniProt predicts a signal peptide or a membrane-spanning region.
Gene: Protein-coding gene on chromosome 6 (49,727,376 to 49,744,437, reverse strand). Ensembl gene ENSG00000096006.
Subcellular location: Secreted
Pathways (Reactome):
Immune System: Neutrophil degranulation
Gene Ontology:
Biological process: defense response; innate immune response
Cellular component: extracellular region; specific granule; extracellular matrix; specific granule lumen; tertiary granule lumen
Genetic constraint (gnomAD): Loss-of-function variants: 17 observed, 17.24 expected, observed/expected ratio (o/e) 0.99, 90% interval 0.67 to 1.48. The upper end of that interval is the gene's LOEUF score, 1.48, which puts it in group 6 of 6, group 1 being the genes least tolerant of losing a copy. Missense variants: 185 observed, 184.7 expected, observed/expected ratio (o/e) 1, 90% interval 0.89 to 1.13. Synonymous variants: 72 observed, 69.4 expected, observed/expected ratio (o/e) 1.04, 90% interval 0.86 to 1.26.
Homologues: Orthologues: macaque CRISP3 (88% identical), dog CRISP3 (68% identical), pig CRISP3 (61% identical), rabbit CRISP3 (59% identical), rat Crisp3 (53% identical), mouse Crisp1 (52% identical), mouse Crisp3 (46% identical), Caenorhabditis elegans scl-12 (25% identical), Caenorhabditis elegans scl-13 (25% identical), Caenorhabditis elegans scl-2 (25% identical), Caenorhabditis elegans scl-1 (24% identical), Caenorhabditis elegans scl-5 (24% identical), and 39 more. Paralogues in human: CRISP2 (67% identical), CRISP1 (40% identical), CRISPLD2 (31% identical), CRISPLD1 (31% identical), GLIPR1 (29% identical), CLEC18A (29% identical), CLEC18C (29% identical), CLEC18B (28% identical), PI15 (26% identical), GLIPR1L1 (26% identical), GLIPR1L2 (26% identical), R3HDML (24% identical), and 1 more.
Diseases named in the same sentence as CRISP3 in open-access papers:
CRISP3 is named in the same sentence as 44 diseases in open-access papers, as found by Europe PMC text mining. Sharing a sentence is not in itself a finding about the gene and the disease. The quoted sentences say what the papers report.
prostate carcinoma (26 papers, 2011 to 2024). A carcinoma that arises from epithelial cells of the prostate gland. "For example, human CRISP3 is dramatically upregulated in prostate cancer and serves as diagnostic and prognostic marker of prostate cancer progression." (PMID 35063506, 2022). "For example, high expression of the cysteine-rich secretory protein CRISP3 (down 130-fold in NuKO cells) has been found in certain subtypes of prostate cancer but down-regulation has been associated with oral squamous cell carcinoma." (PMID 27144453, 2016). "For example, CRISP3 overexpression is strongly associated with PTEN deleted ERG positive prostate cancer." (PMID 25825985, 2015). "In Summary, in this study we confirmed significant association between CRISP3 expression and prostate cancer progression as well as a strong link between CRISP3 expression and each of ERG expression and PTEN genomic deletions." (PMID 24606912, 2014). "CRISP3 has been reported to be one of the top genes that are linked to TMPRSS2-ERG positive prostate cancer with about 53-fold increase when compared with fusion negative prostate cancer." (PMID 24606912, 2014). "The overall data, therefore, indicates that the TMPRSS2-ERG fusion gene and the consequent ERG and CRISP3 overexpression are associated with pathological features related with locally advanced disease in patients with clinically localized prostate cancer." (PMID 21814574, 2011). "Well-known biomarkers for prostate cancer detection like CRISP3 were found to be associated with the gene fusion status." (PMID 22142399, 2011). "The inclusion of benign samples in our gene expression analysis additionally demonstrated that well-known biomarkers for prostate cancer like CRISP3 are associated with the TMPRSS2-ERG fusion status." (PMID 22142399, 2011). "The presence of DES-associated CRISP3 is a harbinger of unfavorable outcomes in prostate cancer and may escalate tumor proliferation and metastatic capabilities by inducing epithelial-mesenchymal transition." (PMID 37070095, 2023). "In the context of prostate cancer, the CRISP3 promoter is regulated by the androgen receptor (AR) through an epigenetic mechanism, and CRISP3 expression is induced by the presence of dihydrotestosterone (DHT) in AR-positive cells." (PMID 39139989, 2024). "Current research on the CRISP3 gene is mainly focused on tumors, and its overexpression was involved in the development of prostate cancer, lung cancer, and breast cancer." (PMID 39609876, 2024). "To further confirm that CRISP3 related to DES promotes prostate cancer proliferation, we carried out experiments in which CRISP3 was either overexpressed or silenced in LNCaP cells." (PMID 37070095, 2023). "It has been reported that CRISP3 is found to be one of the highly up-regulated proteins during the transition of prostate epithelial cells to prostate cancer in healthy individuals." (PMID 37185487, 2023). "Volcano plot shows differential expression of DES, HBB, SLPI, and CRISP3 in prostate cancer bone metastases." (PMID 37070095, 2023). "As a result of the transgenic mouse model of prostate cancer, CRISP3 production greatly contributed to the progression of in situ prostate cancer to invasive prostate cancer in vivo." (PMID 37070095, 2023). "The over-expression of CRISP3 in addition to the down-regulation of PTEN illustrates a subgroup of prostate cancer patients with a high probability of biochemical recurrence." (PMID 36497036, 2022). "On the other hand, the expressions of IGSF1 and CRISP3 are known to be androgen receptor (AR)-dependent and characteristic in prostate cancer cells." (PMID 35976950, 2022). "CRISP3 belongs to a cysteine-rich secretory protein family and has been revealed to be upregulated in prostate cancer." (PMID 34504061, 2021). "Previous reports clearly indicate that the expression of CRISP3 in prostate carcinoma and mammary carcinoma is obviously upregulated." (PMID 34224327, 2021).
prostate carcinoma (continued). "Expression of CRISP3 is prostate-specific, and CRISP3 is up-regulated in a subset of prostate cancers, especially prostate cancer with the TMPRSS2-ERG fusion gene." (PMID 26485759, 2015). "Cysteine- rich secretory protein 3 (CRISP3) prognostic significance in prostate cancer (PCA) has generated mixed result." (PMID 24606912, 2014). "Although our study did not provide any prognostic implication of CRISP3 expression in prostate cancer at the protein level, we were able to confirm significant prognostic value for CRISP3, in the MSKCC and Swedish cohorts." (PMID 24606912, 2014). "Additional analysis supported the implications of high CRISP3 mRNA expression in prostate cancer lethality (p = 0.0086)." (PMID 24606912, 2014). "In the advanced/castration resistant prostate cancer samples (n = 92), CRISP3 protein mean expression levels were the highest with mean intensity of (2.09 ± 0.75) compared to all other types of neoplastic and benign epithelium (p < 0.0001)." (PMID 24606912, 2014). "We next characterized the expression of CRISP3 with prostate cancer subtypes and clinical variables at the mRNA level." (PMID 24606912, 2014). "Cysteine-rich secretory protein 3 (CRISP-3) is an androgen-regulated protein that is upregulated in prostate carcinomas." (PMID 24058910, 2013). "With the development of research, various studies have suggested that CRISP3 may be involved in some pathologic processes, such as dengue, prostate cancer, and breast cancer." (PMID 39624089, 2024). "It appears that CRISP3 may foster prostate cancer proliferation and migration by promoting EMT, as evidenced by the suppression of N-cadherin, Vimentin, and Snail markers of EMT after knocking down hsa_circ_0003823 protein." (PMID 37070095, 2023). "The observation that the expression of both CRISP2 and CRISP3 is increased in prostate cancer, whereas that of PSP94 is decreased, suggests that these two proteins could exert opposing functions during cancer progression." (PMID 35063506, 2022). "CRISP3 has been found to be a prominent marker of prostate cancer gene expression, ovarian cancer." (PMID 33624385, 2021). "Furthermore, a publication has elucidated that CRISP3 facilitated cell motility and invasion in prostate cancer." (PMID 34504061, 2021). "CRISP3 has been previously reported to be overexpressed in prostate cancer." (PMID 24606912, 2014). "Others noted that CRISP3 expression increases more than 50 fold in prostate cancer." (PMID 24606912, 2014). "In prostate cancer, CRISP3 could drive invasion and migration of cancer cells." (PMID 36263172, 2022). "SOX11, CRISP3, KIF18B, and MELK expression levels have also been found to be positively correlated with poor prostate cancer patient prognostic outcomes, while ZNF556 has been associated with poor colon cancer patient prognosis." (PMID 36245556, 2022). "In contrast to CRISP3, PSP94 expression is downregulated in prostate cancer, suggesting a protective role in prostate carcinogenesis." (PMID 35063506, 2022). "CRISP3 and KCNMA1 have been demonstrated to be correlated with metastasis potential in prostate cancer and breast cancer, respectively." (PMID 23451142, 2013). "Further studies to elucidate the molecular network connecting CRISP3, ERG and PTEN and to validate their combined prognostic role may be of added value in stratifying patients with prostate cancer, specifically those with Gleason score 6&7." (PMID 24606912, 2014). "Although the gene signatures of all forms of urogenital cancer/diseases are largely unknown, the six known prostate cancer genes of AGR2, AMACR, CRISP3, ERG, HPN, and PCA3 are at or below background, for example, in bladder cancer." (PMID 23029164, 2012).
prostate carcinoma (continued). "Using a histogram format for data display, all signal counts for the selected prostate cancer genes were at background for P08-022N: AGR2 = 0.08 [(8 counts, relative to B2M = 100 (10,000 counts)], AMACR = 0.46, CD90v = 0.02, CRISP3 = 0.25, ERG = 0.1, HPN = 0.04, PCA3 = 0.09 (data entries in blue)." (PMID 23029164, 2012). "We also aimed to validate the prognostic value of CRISP3 in conjunction to the molecular subtype of PCA with ERG and PTEN genomic aberrations and to utilize bioinformatics to delineate possible genetic connections and pathways related to this molecular subtype of prostate cancer." (PMID 24606912, 2014). "The tight link between CRISP3 expression, ERG gene rearrangements and/ or PTEN deletions in the three cohorts of prostate cancer studied, suggest the presence of distinct molecular alterations in this subgroup of tumors that may have additional clinical implication if assessed collectively." (PMID 24606912, 2014).
breast carcinoma (15 papers, 2013 to 2025). "Immunohistochemistry (IHC) further confirmed that HEMTIRGs expression levels were strongly associated with breast cancer, with CRISP3 showing the most pronounced upregulation." (PMID 41200166, 2025). "Among them, AZGP1 and CRISP3 are associated with breast cancer invasiveness, while SCGB2A2 and SCGB1D2 serve as common markers for disseminated tumor cells (DTCs)." (PMID 40838787, 2025). "In addition, the dopamine receptor D5 gene (DRD5) was described to be involved in tumor growth inhibition via autophagic cell death, NCOR2 was described to be associated with drug resistance in breast cancers and CRISP3 was associated with prostate and ovarian cancers." (PMID 33400739, 2020). "Among the significant differentially expressed genes (DEGs) identified, CRISP3 plays a pivotal role in breast cancer by regulating tumor cell migration, invasion, and immune modulation." (PMID 41223185, 2025). "Consistently, in patients with mammary carcinoma, it has been found that higher expression of CRISP3 was connected to a significantly decreased disease-free survival and overall survival." (PMID 41200166, 2025). "The knockdown of CRISP3 can greatly inhibit the migration and invasion of mammary carcinoma cells and the ERK1/2 MAPK signaling pathway." (PMID 39804726, 2025). "In domains 4 and 13, 2 differentially expressed genes, IGFBP5 and CRISP3, have dense linkages with the treatment of mammary carcinoma." (PMID 39804726, 2025). "In vitro functional assays demonstrated that CRISP3 promoted malignant phenotypes of breast cancer cells under hypoxic conditions through activation of the IL-17/AKT signaling pathway." (PMID 41200166, 2025). "The CXCL14, COX6C, and CRISP3 have been verified are highly expressed genes of invasive dual carcinoma (IDC) in breast cancer." (PMID 39764614, 2024). "The low expression of CRISP3 has been reported to predict a favorable prognosis in patients with mammary carcinoma, and also weakened the migration and invasion of mammary carcinoma cells." (PMID 34504061, 2021). "A previous study indicated that CRISP3 was involved in the invasion and migration of mammary cancer and that CRISP3 was closely correlated with poor prognosis in mammary cancer patients." (PMID 34224327, 2021). "CRISP3 was also considered a marker for clinical outcomes in patients with mammary carcinoma." (PMID 39804726, 2025). "A significant higher mRNA and protein levels of CRISP3 were seen in T-47D as well as SK-BR-3 human breast cancer cell lines compared with those in other types of mammary carcinoma cells, and knockdown of CRISP3 resulted in weakened migration or invasion abilities." (PMID 41200166, 2025). "Notably, our experimental work validated that CRISP3 is a key HEMTIRG that modulates the biological functions of breast cancer cells under hypoxic conditions through the IL-17/AKT signaling pathway." (PMID 41200166, 2025). "Furthermore, dysregulated CRISP3 was observed in cervical cancer, gallbladder cancer, and breast cancer." (PMID 39624089, 2024). "And in mammary carcinoma, patients with low expression levels of CRISP3 had a favorable prognosis." (PMID 36263172, 2022).
oral squamous cell carcinoma (5 papers, 2016 to 2024). "In oral squamous cell carcinoma, a decrease in CRISP3 expression was observed, especially in early stages, where loss of CRISP3 DNA copy number was detected." (PMID 39139989, 2024). "Furthermore, it was reported that in oral squamous cell carcinoma (OSCC), CRISP3 was down-regulated in tumor tissues, and its DNA copy number loss was found in T1/T2 classification and down-regulated CRISP3 may be a protective biomarker in OSCC22." (PMID 37185487, 2023).
ovarian carcinoma (5 papers, 2020 to 2026). A malignant neoplasm originating from the surface ovarian epithelium. "There are two identified biomarkers, CRISP3 and MUC9, that might be used for ovarian cancer early diagnosis and prevention." (PMID 36076202, 2022).
cervical cancer (4 papers, 2021 to 2025). A primary or metastatic malignant neoplasm involving the cervix. "Cysteine-rich secretory protein 3 (CRISP3) encodes the extracellular matrix protein; it was reported to be significantly downregulated in cervical cancer, especially in cases with HPV16 infection, which was associated with poorer overall survival." (PMID 39769169, 2024). "During the progression of cervical cancer, other up‐regulated genes, such as CRISP3 (gene ID: 10321) belongs to the family of cysteine‐rich secreted proteins (CRSP), which is involved in the defense response against foreign material damage and the natural immune response of the reproductive system." (PMID 33624385, 2021). "Cysteine-rich secretory protein 3 (CRISP3) emerges as a potential biomarker in the study of many cancers, including cervical cancer (CC)." (PMID 39139989, 2024). "During the progression of cervical cancer, from normal cervical tissues to CIN 1, 2 and 3, the gradually down‐regulated genes we confirmed were CRISP3, CRISP2, PPP1R3C, and DSG1." (PMID 33624385, 2021).
bladder cancer (3 papers, 2012 to 2023). "The overall function of the protein is still unknown, but it has been found to bind cysteine-rich secretory protein 3 (CRISP3), and has been associated with breast, liver, pancreas and bladder cancer, as well as with steroid-resistant nephrotic syndrome." (PMID 26555091, 2016).
multiple myeloma (3 papers, 2022 to 2024). "Conversely, in silico research revealed an increase of CRISP3 expression in patients diagnosed with multiple myeloma (MM)." (PMID 39139989, 2024). "A statistically significant reduction in TIMP1 expression was observed, accompanied by an increase in CD82B and CRISP3 expression, in the myeloma (MM) group with a favorable prognosis compared to the MM group with an unfavorable prognosis (p < 0.05)." (PMID 39769169, 2024). "CRISP3 is activated in mouse B cells and may be a potential biomarker of multiple myeloma." (PMID 35627314, 2022).
prostate tumors (3 papers, 2014 to 2024). "CRISP3 was shown to be elevated in prostate tumors and linked to cancer progression from primary to metastatic prostate cancer." (PMID 38918474, 2024). "For example, cysteine-rich secretory protein 3 (CRISP3) gene expression was found to be associated with the ERG condition, since it was overexpressed in TMPRSS2-ERG fusion-positive prostate tumors as compared to normal tissue." (PMID 24739220, 2014). "CRISP3 was upregulated; conversely, OGN, SPOCK3, COL4A6, CCBE1, and FLRT3 were downregulated in prostate tumor tissues." (PMID 37251946, 2023).
Sjögren’s syndrome (3 papers, 2017 to 2021). "In humans, CRISP3 was described in several tissues and differences in its expression are associated with different pathologies such as prostate cancer, breast cancer, Sjögren’s syndrome, varicocele, prostatitis and endometriosis, among others." (PMID 34970552, 2021). "Lane and co-authors found significantly lower levels of CRISP-3 in the saliva from patients with Sjögren’s syndrome compared to heathy controls and concluded that the CRISP-3 deficiency in Sjögren’s syndrome might be caused by low levels of dehydroepiandrosterone prohormone." (PMID 32272779, 2020). "Indeed, Sjögren’s syndrome patients demonstrate marked decreases in their serum DHEA and androgen levels and reduced androgen receptor activity, as revealed by the decreased expression of CRISP-3." (PMID 28877240, 2017).
teratozoospermia (3 papers, 2022 to 2025). "Among the six differentially expressed microRNAs, miR-182-5p has been reported to constitutea regulatory network with CRISP3 in the seminal plasma fluid of teratozoospermia patients, indicating miR-182-5p could be a possible biomarker for teratozoospermia." (PMID 38001535, 2023).
carcinoma in situ (2 papers, 2023). "CRISP3 belongs to a large family of cysteine-rich secretory proteins and is essential for the development of invasive PCa in vivo from carcinoma in situ as well as for AR-independent transcriptional processes." (PMID 37188204, 2023). "CRISP3 promotes the progression of PCa from carcinoma in situ to invasive carcinoma via changes in cell adhesion pathways." (PMID 37251946, 2023).